LGALS3 (galectin 3)
Diseases named in the same sentence as LGALS3 in open-access papers (continued):
Sharing a sentence is not in itself a finding about the gene and the disease.
Listeria infection (3 papers, 2020 to 2026). "Furthermore, the molecular mechanisms underlying the contribution of accumulated galectin-3 to autophagic inhibition in Listeria infection remain to be determinated." (PMID 33663512, 2021). "Additionally, we also looked at endolysosomal membrane permeabilization during Listeria infection and found that while the wild-type bacteria induced Galectin-3 positive endolysosomal damage, the Listeriolysin O-deficient Δhly mutant did not." (PMID 41266655, 2026). "We also found that Listeria monocytogenes infection triggered galectin-3 accumulation around bacteria-containing phagosomes, in which the membrane integrity was compromised by the bacterial pore-forming cytolysin listeriolysin (LLO), as revealed by electron microscopy." (PMID 33663512, 2021).
liver failure (3 papers, 2021 to 2025). A liver disease characterized by the liver losing or has lost all of its function. "The relationship between galectin-3 and the risk of liver failure was explored in two study cohorts, both of which selected the healthy volunteers as the control subjects." (PMID 34778306, 2021). "Serum galectin-3 level was significantly higher in the patients with liver failure compared to the healthy volunteers (MD = 0.44, 95% CI = 0.23–0.66, p < 0.001) with a significant heterogeneity (I2 = 97.8%, p < 0.001)." (PMID 34778306, 2021).
medullary carcinoma (3 papers, 2003 to 2025). "Immunohistochemistry (ELISON method) showed: in the medullary carcinoma area: PCK (+), CEA (+), CT (focal cytoplasmic weak +), INSM1 (+), Syn (+), CgA (+), Galectin-3 (-), TG (-), CK19 (-), Ki-67 (+, 3%)." (PMID 41323380, 2025).
metastatic prostate carcinoma (3 papers, 2020 to 2023). A carcinoma that arises from the prostate gland and has spread to other anatomic sites. "Furthermore, patients with metastatic prostate cancer had higher levels of serum galectin-3 compared with control subjects without cancer." (PMID 38139416, 2023).
muscular dystrophy (3 papers, 2017 to 2023). Muscular dystrophy (MD) refers to a group of more than 30 genetic diseases characterized by progressive weakness and degeneration of the skeletal muscles that control movement. "Lgals3 (gal-3) has been implicated in the development of fibrosis, suggesting that gal-3+ macrophages promote fibrosis during muscular dystrophy." (PMID 37418531, 2023). "Meanwhile, endogenous galectin-3 expression, which is required for myogenic differentiation, enhances the efficiency of myogenesis in a mouse model of muscular dystrophy." (PMID 34444962, 2021). "Clearly, the function of galectin-3 is dependent on type of injury and the context of organ damage and it cannot be ruled out that modulating galectin-3 expression in other types of muscular dystrophy could be beneficial." (PMID 28281577, 2017). "Given the selective induction of Lgals3 and Spp1 in dystrophic muscle macrophages, we hypothesize that this transcriptional profile defines a fibrogenic macrophage that promotes fibrosis during muscular dystrophy." (PMID 37418531, 2023). "The role of galectin-3 in muscular dystrophy has never been investigated previously." (PMID 28281577, 2017). "All muscular dystrophy hallmarks (degeneration/regeneration cycles, inflammatory response, fibrosis) were clearly visible in various 3-week-old dy3K/dy3K, dy3K/OPN and dy3K/GAL muscles, but not in osteopontin or galectin-3 knockout mice." (PMID 28281577, 2017).
myeloid leukemia (3 papers, 2016 to 2024). A clonal proliferation of myeloid cells and their precursors in the bone marrow, peripheral blood, and spleen. "In the U937 and HL60 myeloid leukemia cell lines, galectin-3 expression was observed to be higher compared to the lymphoid leukemia cell lines Nalm6 and SUP-B15, but lower than in Raji." (PMID 38184596, 2024). "In addition, the galectin-3-silenced human myeloid leukemia cell lines THP1 and U937 were used to confirm the identified effects." (PMID 26934444, 2016).
non-Hodgkin lymphoma (3 papers, 2010 to 2022). Distinct from Hodgkin lymphoma both morphologically and biologically, non-Hodgkin lymphoma (NHL) is characterized by the absence of Reed-Sternberg cells, can occur at any age, and usually presents as a localized or generalized lymphadenopathy associated with fever and weight loss. "Interestingly, the expression levels of galectin-3 in sera of non-Hodgkin’s lymphoma patients were related to cardiovascular events, and serum galectin-3 might be a prognostic biomarker for cumulative cardiovascular events." (PMID 35677161, 2022). "Galectin-3 expression has never been associated with prognosis in non-Hodgkin’s lymphomas." (PMID 23658855, 2010).
ocular infections (3 papers, 2019 to 2024). "Galectin-3 has been implicated in the attachment and entry of the herpes simplex virus (HSV) during ocular infections, as well as in herpetic allodynia, a type of pain induced by HSV-1 infection." (PMID 37298569, 2023). "MUC1 is thought to prevent damage and infection of the ocular surface epithelium through interactions with galectin-3, however animal models and in vivo work have found inconsistent expression and functions of MUC1 in ocular infection and disease." (PMID 31552195, 2019).
osteoradionecrosis (3 papers, 2011 to 2023). Necrosis of bone following radiation injury. "In osteoradionecrosis-related mucoperiosteal tissues, increased TGFβ1 and Smad-2/3, together with radiation-induced Galectin-3 were associated with perpetuation of fibrotic soft tissue remodeling and inhibition of re-epithelization {Cao, 2002 #4522}." (PMID 21726429, 2011). "In contrast, BRONJ-related jaw soft tissue and osteoradionecrosis-adjacent tissue showed Galectin-3 staining throughout the tissue samples." (PMID 21726429, 2011). "However, Galectin-3 expression was significantly higher in the BRONJ samples than in the osteoradionecrosis samples (p < 0.044)." (PMID 21726429, 2011). "The potential role of Galectin-3 in preventing an intraoral immune response in BRONJ is further substantiated by the significantly higher expression (p(0.044) of Galectin 3 in BRONJ-affected tissue compared to osteoradionecrosis-related tissue, which is characterized by local inflammation." (PMID 21726429, 2011). "Galectin-3 staining was significantly (p < 0.025) increased in both the BRONJ and the osteoradionecrosis (p < 0.038) groups compared to the normal tissue group." (PMID 21726429, 2011). "Homogenous cytoplasmic Galectin-3 staining was observed in the fibrous tissue stroma cells between the periosteum and the epithelium of the oral mucosa in BRONJ-affected and osteoradionecrosis-related soft tissue." (PMID 21726429, 2011). "The overall cellular density of Galectin-3-expressing cells was significantly increased in the BRONJ (p < 0.025) and osteoradionecrosis-adjacent tissues (p < 0.038) compared to the periosteal fibrous tissue of the normal jaw." (PMID 21726429, 2011).
pilocytic astrocytoma (3 papers, 2017 to 2023). Pilocytic astrocytoma is a rare subtype of low-grade glioma of the central nervous system characterized by a well circumscribed, often cystic, brain tumor with a discrete mural nodule and long, hair-like projections that extend from the neoplastic astrocytes. "Distinctly high expression of LGALS3 was observed in pilocytic astrocytoma and GBM, both with a diffuse pattern." (PMID 32528967, 2020). "In conclusion, we have shown that LGALS3 is a novel biomarker that is highly expressed in pilocytic astrocytoma, GBM, and IDH wild-type LGG." (PMID 32528967, 2020). "However, we think LGALS3 only has limited auxiliary diagnostic ability due to emerging molecular markers, such as IDH mutation, 1p/19q codeletion, and BRAF-KIAA1549 fusion (pilocytic astrocytoma's characteristic molecular alteration)." (PMID 32528967, 2020).
placental insufficiency (3 papers, 2020 to 2024). Failure of the placenta to deliver an adequate supply of nutrients and oxygen to the fetus. "Furthermore, the development of FGR is accompanied by an altered pattern of circulating galectin-3 levels and galectin-3 deficiency in mouse pregnancy leading to placental insufficiency and the subsequent development of FGR." (PMID 33808559, 2021). "In addition, Lgals3+/− implantations carried by Lgals3−/− dams displayed a decreased fetal/placental weight ratio, indicative of placental insufficiency, along with a reduction of PAS+ glycogen cells in the junctional zone." (PMID 32703931, 2020).
pneumococcal pneumonia (3 papers, 2016 to 2023). A febrile disease caused by STREPTOCOCCUS PNEUMONIAE. "Galectin-3 deficient mice showed decreased neutrophil influx and increased bacterial load in response to pneumococcal pneumonia, indicating galectin-3 is a Spn-specific integrin that aids in migration of neutrophils." (PMID 35646729, 2022).
polycystic ovary syndrome (3 papers, 2023 to 2024). A disorder that manifests as multiple cysts on the ovaries. "This study explores the impact of metformin dosage and hyperprolactinemia on galectin-3 levels in women with Polycystic Ovary Syndrome (PCOS), providing novel insights into their roles in the metabolic and hormonal management of the condition." (PMID 39958874, 2024).
renal carcinoma (3 papers, 2011 to 2024). A carcinoma arising from the epithelium of the renal parenchyma or the renal pelvis. "Recent work indicated that hypoxia promotes Lgals3 activity depending on HIF-1α in renal carcinoma cells." (PMID 39595213, 2024). "As shown in other studies, galectin-3 was highly expressed in the renal cancers." (PMID 22039439, 2011).
rheumatic diseases (3 papers, 2018 to 2025). "The diagnostic accuracy (ACC) of galectin-3 was high and similar in all rheumatic diseases (about 80%)." (PMID 33076422, 2020). "Due to these facts, we try to assess the serum galectin-3 levels, its diagnostic values and potential association with progression of disease in the most common rheumatic diseases." (PMID 33076422, 2020). "The results of this study showed that galectin-3 had a high diagnostic specificity in all rheumatic diseases accompanied by diagnostic sensitivity placed between ESR and CRP values." (PMID 33076422, 2020). "While increased serum levels of galectin-3 have been previously reported in patients with rheumatic diseases, this is probably the first study investigating the diagnostic values of serum galectin-3 in the diagnosis of selected rheumatic diseases." (PMID 33076422, 2020). "Moreover, galectin-3 due to the high diagnostic power can be a valuable surrogate marker for the diagnosis of rheumatic diseases, particularly RA and SSc." (PMID 33076422, 2020). "Moreover, we showed that galectin-3 had a very high diagnostic power (area under the ROC curve) for all tested rheumatic diseases, making galectin-3 a good diagnostic marker." (PMID 33076422, 2020). "Therefore, inflammation and dysfunction of immune response may increase serum galectin-3 concentration in patients with different rheumatic diseases." (PMID 33076422, 2020). "The positive predictive value (PPV) of galectin-3 was higher than PPV of CRP and ESR in all rheumatic diseases." (PMID 33076422, 2020). "The analysis of variance revealed that rheumatic diseases did not affect the galectin-3 concentration (H = 0.395, p = 0.821), CRP (H = 4.798, p = 0.091), PLT (H = 5.061, p = 0.080), and HGB (H = 3.935, p = 0.140), but effect the ESR (H = 13.001, p = 0.002)." (PMID 33076422, 2020).
streptococcal pneumonia (3 papers, 2013 to 2025). A febrile disease caused by streptococcus pneumoniae. "Furthermore, in an in vivo mouse model of streptococcal pneumonia, neutrophil extravasation was closely linked to the accumulation of galectin-3 in the alveolar space, a process that occurred independently of β2-integrin." (PMID 39941305, 2025).
triple-negative breast carcinoma (3 papers, 2014 to 2024). An invasive breast carcinoma which is negative for expression of estrogen receptor (ER), progesterone receptor (PR), and human epidermal growth factor receptor 2 (HER2). "Galectin-3 has a relatively high level of expression in triple-negative breast cancers and is a potential marker for this disease." (PMID 25254965, 2014).
ulcers (3 papers, 2020 to 2025). "Pointing at a role for galectin-3 at this interface of internal and external factors, galectin-3 null mice exhibited a different gut microbiome than controls in a model of nonsteroidal anti-inflammatory drug-induced ulcers." (PMID 40649879, 2025).
uterine tumor (3 papers, 2014 to 2024). "In the current research, we have evaluated the expression of PD-L1, PD-L2, B7-H4, IDO, galectin-1 and galectin-3 in uterine tumors and documented the arginase-1 activity and MDSC infiltration in these tumors." (PMID 24658839, 2014). "In addition, we have analyzed the expression of galectin-1 and 3 in uterine tissue samples by ELISA and confirmed galectin-3 expression on cellular subtypes in uterine tumor specimens by flow cytometry." (PMID 24658839, 2014). "In conclusion, we report the presence of the immune checkpoints PD-L1/PD-L2 and B7-H4 in uterine tumors as well as the presence of the immune inhibitory molecules IDO, arginase-1, galectin-1 and galectin-3 and the immunosuppressive MDSC." (PMID 24658839, 2014). "In an attempt to shed more light on the immunosuppressive environment in uterine tumors, we analyzed the presence of PD-L1, PD-L2, B7-H4, indoleamine 2,3-dioxygenase (IDO), galectin-1, galectin-3, arginase-1 activity and myeloid-derived suppressor cell (MDSC) infiltration." (PMID 24658839, 2014).
ventricular tachycardia (3 papers, 2021 to 2023). A disorder characterized by an electrocardiographic finding of three or more consecutive complexes of ventricular origin with a rate greater than a certain threshold (100 or 120 beats per minute are commonly used). "Emphasizing fibrosis as the source of the disease, the authors found galectin-3 to be predictive of ventricular tachycardia and ventricular fibrillation in this cohort." (PMID 35410028, 2022).
viral myocarditis (3 papers, 2019 to 2020). Myocarditis that is caused by an infection with a viral agent. "Therefore, we conducted such a time-course study and observed that galectin-3 was up-regulated in degenerated fibrotic lesions 96 hours after viral inoculation, an early phase of viral myocarditis." (PMID 30673749, 2019).
acute liver failure (2 papers, 2022 to 2023). Rapid deterioration of liver function causing encephalopathy and coagulopathy. "In the human liver, LGALS3 expression was found slightly but significantly increased in patients suffering from alcoholic hepatitis and hepatitis B virus-associated acute liver failure and significantly decreased in obese subjects in response to a short-term low-fat hypocaloric diet." (PMID 35046474, 2022).
acute pancreatitis (2 papers, 2016 to 2024). An acute inflammatory process that leads to necrosis of the pancreatic parenchyma. "Acute pancreatitis was induced by ligation of the bile-pancreatic duct in wild-type and Galectin-3-deficient C57BL/6 mice." (PMID 38927046, 2024). "The deletion of Galectin-3 ameliorates acute pancreatitis characterized by lowering serum amylase concentration and pancreatic trypsin activity, and attenuating of the histopathology of the lung." (PMID 38927046, 2024).
acute respiratory failure (2 papers, 2024). Life-threatening respiratory failure that develops rapidly. "This study reports training by lipopolysaccharide to expand neutrophils expressing the anti-bacterial galectin-3 protein defending mice from a lethal bacterial infection, a similar signature associated with survivors of respiratory failure in humans." (PMID 38830855, 2024). "Taken together, our study provides impetus for harnessing the potential of galectin-3-expressing neutrophils to protect from lethal infections and respiratory failure." (PMID 38830855, 2024).
age-related macular degeneration (2 papers, 2023 to 2025). Age-related loss of vision in the central portion of the retina (macula), secondary to retinal degeneration. "Further on, in a mouse model for wet age-related macular degeneration (AMD), a very common sight-threatening disease in elderly humans, the inhibition of galectin-3 led to smaller chorioretinal neovascularization and less subretinal fibrosis (CNV)." (PMID 40806748, 2025).
aspergillosis (2 papers, 2020 to 2021). Aspergillosis is an infection, growth, or allergic response caused by the Aspergillus fungus. "Here we show that galectin-3 expression is markedly up-regulated in mice and humans with pulmonary aspergillosis." (PMID 32750085, 2020). "High levels of extracellular galectin-3 were found in the serum of mice infected with A. fumigatus, as well as human patients with pulmonary aspergillosis." (PMID 32750085, 2020). "When compared with healthy controls, serum galectin-3 levels were significantly elevated in patients with both forms of pulmonary aspergillosis but not in patients with other pulmonary infections or inflammatory conditions." (PMID 32750085, 2020).
attention deficit-hyperactivity disorder (2 papers, 2020). A disorder characterized by a marked pattern of inattention and/or hyperactivity-impulsivity that is inconsistent with developmental level and clearly interferes with functioning in at least two settings (e.g. at home and at school). "In addition, the majority of data considering a potential role of Galectin-3 in attention deficit hyperactivity disorder (ADHD) was obtained due to fact that the spontaneously hypertensive rats (SHR) were found to be an experimental model of ADHD." (PMID 32455781, 2020).
autoimmune myocarditis (2 papers, 2020). Autoimmune myocarditis is an autoimmune disease that affects the heart. "Furthermore, we showed that in mouse experimental model of autoimmune myocarditis Galectin-3 had a protective role on disease development." (PMID 32455781, 2020).
bladder transitional cell carcinoma (2 papers, 2010 to 2024). The most common morphologic subtype of urinary bladder carcinoma (over 90% of cases). "Research on galectin-3 in bladder urothelial carcinomas is limited, with discrepancies in sample sizes, antibody clones, and application methods contributing to seemingly contradictory findings." (PMID 39451592, 2024). "The expression of galectin-1 and galectin-3 was investigated in 38 human bladder transitional cell carcinomas of different histological grade and clinical stage and in five normal urothelium samples." (PMID 23658855, 2010). "Given the complex roles of galectin-3, particularly in the epithelial-to-mesenchymal transition (EMT), and the variability in its expression reported in bladder urothelial carcinomas, this study seeks to elucidate several key aspects." (PMID 39451592, 2024).
bone tumor (2 papers, 2021). "Considering the crucial role of LGALS3 in modulation of the bone tumor microenvironment and that bone metastases are a common clinical outcome of various solid cancers, the activities and mechanisms of other cancer‐derived LGALS3 underlying bone metastases are worthy of being further investigated." (PMID 33643786, 2021).
brain inflammation (2 papers, 2021 to 2024). "Another study pointed out that the OA2 microglial cell subset promotes age-related brain inflammation by expressing some unique inflammatory signals (such as Lgals3 Cst7 Ccl4 Ccl3 Il1b)." (PMID 39440247, 2024).
Cholestatic liver disease (2 papers, 2021 to 2024). "Moreover, increased galectin-3 in PSC may also initiate studies to evaluate galectin-3-blocking agents in cholestatic liver diseases." (PMID 38731984, 2024).